TYR (tyrosinase)
Diseases named in the same sentence as TYR in open-access papers (continued):
Sharing a sentence is not in itself a finding about the gene and the disease.
tumor (256 papers, 1995 to 2026). "These DCs are isolated from the patient, pulsed with tumor-associated antigens such as gp100 or tyrosinase peptides, or transfected with tumor-derived RNA through electroporation, and subsequently reinfused to induce a tumor-specific T cell response." (PMID 40725830, 2025). "Tyrosinase, a crucial enzyme for melanin production, is a tumor-associated antigen used for DNA vaccine formulation." (PMID 36670786, 2023). "The Melanoma Associated Antigen Gene (MAGE) family proteins, tyrosinase, and the Premelanosome Protein gp100 are UM tumor-associated antigens (TAA) that are recognized by cells of the immune system." (PMID 34830841, 2021). "Considering whole proteins, our results show that PDC*line cells transduced by the construct encoding the proteins gp100 and tyrosinase were able to present tumour peptides to T-cell clones as efficiently as the peptide-loaded PDC*line." (PMID 33578850, 2021). "Immunogenicity can be restored by reintroducing differentiation antigens as it has been done by using nanoparticulate liposomal RNA vaccine encoding tumor-associated antigens such as tyrosinase." (PMID 33276788, 2020). "In contrast to cancer/testis antigens, tumor-associated antigens (TAAs), such as gp100, tyrosinase or EGFR, are overexpressed on tumor cells and are shared in a bigger patient population." (PMID 31040852, 2019). "To elicit a strong antitumor immune response, we created a dendritic cell (DC) vaccine loaded with three full-length tumor-associated antigens: Tyrosinase, MART-1, and MAGE-A6 (TMM2)." (PMID 30400835, 2018). "Intracellular expression of tumor-associated antigens gp100 and tyrosinase after electroporation was variable, but for each patient expression of either gp100 or tyrosinase was at least 30 %." (PMID 26861670, 2016). "While univariate analysis showed sex and primary tumour location associated with positive RT-PCR, multiple regression analysis revealed clinical stage and detection of tyrosinase transcripts in peripheral blood as best prognostic factors." (PMID 10638977, 2000). "Two clinical studies registered on ClinicalTrials.gov evaluated chimeric DNA vaccines encoding xenogeneic tumor antigens such as mouse tyrosinase and gp100, leveraging the concept of breaking tolerance to self-antigens with high sequence homology to human proteins." (PMID 40725830, 2025). "For example, Engelhorn and colleagues introduced mutations into the coding sequence of two syngeneic tyrosinase-related TAAs and showed that the introduced mutations could break self-tolerance and enhance anti-tumor immunity." (PMID 38932353, 2024). "Indeed, due to its high mutational load as well as the presence of tumor-associated antigens (as gp100, tyrosinase, and Melan-A) that can elicit immune system activation, SKCM is considered one of the best targets in the field of anti-tumor immunotherapy." (PMID 35725560, 2022). "Independently of tyrosinase’s pigmentary function, the loss or reduction in tyrosinase activity could also benefit tumor growth and metastasis." (PMID 36556369, 2022). "Indeed, in the TCGA SKCM collection a higher incidence of somatic mutation of the TYR gene was seen in AHM compared with PM tumor samples." (PMID 32966289, 2020). "TYR transfection of tumours, causing them to synthesise melanin which is subsequently irradiated by radiolabelled benzamides, may be an effective method of unsealed source therapy." (PMID 26483258, 2015). "It is possible that melanin production may cause significant decreases in tumor growth over longer periods of time, however, the inducible tyrosinase expression system prevents cells from requiring more than 1 week under tyrosinase induced expression with DOX." (PMID 24936769, 2014).
tumor (continued). "Initial clinical studies demonstrated potential benefits, including extended survival times and the induction of anti-tyrosinase antibodies, which suggest that a xeongenic tumor-associated antigen could serve as a target to generate clinically effective anti-tumor T-cell responses." (PMID 37235419, 2023). "We observed a significant increase over time in the interactions between SOX2/OLIG2 high tumor cells and different tumor cell populations, including p-TYR high and translating GFAP- tumor cells." (PMID 41568176, 2026). "The TYR-activated prodrug group (Pd1-Pd2-SA@Gel) displayed a superior tumor inhibition efficacy compared to other treatment groups." (PMID 40651969, 2025). "Our recent study shows nanobiotherepeutic Polyhemoglobin-Tyrosinase-Nanocapsules (PolyHb-Tyr-Nano) have strong anti-tumor abilities in multiple cancer lines." (PMID 40370596, 2025). "Inhibition of tyrosinase enzymes directly affects melanin production and helps to remove skin hyperpigmentation." (PMID 41373531, 2025). "Tyrosinase inhibition represents an attractive challenge to fight skin hyperpigmentation for medicinal and cosmeceutical application." (PMID 40557312, 2025). "In this study, we show that nanocapsules containing polyhemoglobin–tyrosinase (PolyHb-Tyr-nano) can introduce tyrosinase intracellularly to activate quercetin and suppress tumor growth in normal hepatocytes." (PMID 40867327, 2025). "Heterogeneous tumour growth and repigmentation of the B16‐G4F tumour led us to develop a non‐pigmented cell line (B16‐OVAmTYR−/−) by tyrosinase invalidation using CRISPR/Cas9." (PMID 40898695, 2025). "Compared to mice injected with the empty vector, those injected with the EGR3 adenovirus exhibited smaller tumor volume and weight increased collagen content, and decreased expression levels of tyrosinase required for melanin formation." (PMID 38973154, 2024). "We recently showed that AAV vaccines carrying tumor antigens such as glycoprotein 100, tyrosinase, and TRP-1 protected C57BL/6 mice from B16F10 tumors to different extents." (PMID 39559560, 2024). "Many phenolic compounds are responsible for numerous biological activities, including anti-tumor, anti-inflammatory, antioxidant, antihyperglycemic, antiosteoporotic, anti-tyrosinase and antimicrobial activities." (PMID 36675891, 2023). "We clearly observed that loss of CXCR2 expression in tyrosinase-expressing cells where there was expression of mutant BRAF and loss of PTEN resulted in reduced tumor growth and lowered incidence of tumor formation." (PMID 37270599, 2023). "TIL1383I is a prototypical class-mismatched TCR, cloned from a CD4+ T cell but recognizing the tyrosinase tumor antigen presented by the class I MHC HLA-A2 in a fully functional manner." (PMID 36424374, 2022). "It inhibited the activity of tumor cells, the activity of intracellular tyrosinase, and the synthesis of melanin." (PMID 36185429, 2022). "Cytotoxic T cell responses against these self-antigens not only exert an anti-tumour effect but also destroy melanocytes that express normal levels of tyrosinase, TRP, and other proteins, leading to the occurrence and persistence of autoimmune vitiligo." (PMID 36414662, 2022). "Our patient had many characteristics of the TYR subgroup including age at presentation (<1 yr), tumor location (infratentorial), and genetic findings." (PMID 35967099, 2022). "It is important to note that reactivity was practically nil before vaccination (PRE sample), although PMEL and tyrosinase (TYR) were strongly expressed in the patient’s tumor." (PMID 35432383, 2022).
tumor (continued). "Silencing lncRNA-Gm31932 not only inhibits the growth and size of tumors, but also increase the melanin content and tyrosinase activity in tumor tissues." (PMID 35393397, 2022). "The interest in circulating long RNAs arose back in the 1990s, when blood levels of TYR (tyrosinase) mRNA were investigated in CM and UM patients to detect circulating tumor cells (CTCs)." (PMID 34885029, 2021). "Anlotinib is a multi-target tyrosinase inhibitor that blocks tumor angiogenesis by inhibiting VEGFR/FGFR/PDGFR and can also restrain tumor cell proliferation by blockade of FGFR/c-KIT20,21,27." (PMID 33710812, 2021). "A series of 14 metastatic UMV patients was treated with dendritic cell vaccination, using antigen-presenting cells loaded with gp100 and tyrosinase: a tumor specific response was observed in 29% of the patients, while median overall survival was 19.2 months." (PMID 34830841, 2021). "Here, we demonstrate improved visualization of cancer-targeting bacteria using OA imaging and E. coli engineered to express tyrosinase, which uses L-tyrosine as the substrate to produce the strong optoacoustic probe melanin in the tumor microenvironment." (PMID 34952915, 2021). "This is the first study of α-amyrin and β-amyrin to consider anti-tyrosinase potential, and our results support the development of α-amyrin and β-amyrin as therapeutics for skin hyperpigmentation." (PMID 34885832, 2021). "Tumors of animals injected with tyrosinase-expressing E. coli showed strong melanin signals, allowing to resolve bacterial growth in the tumor over time using multispectral OA tomography (MSOT)." (PMID 34952915, 2021). "The levels of TYR in the tumor and metastatic organs analyzed by Western blot were consistent with the fluorescence results, in which TYR in the tumor, lung, and spleen was found to be over-expressed." (PMID 34436092, 2021). "Here, we use MSOT to monitor bacterial targeting, infiltration and proliferation specifically in the tumor microenvironment based on E. coli that express the transgene for tyrosinase." (PMID 34952915, 2021). "In their study they showed the adoptively transferred Tregs to inhibit effector T cells, including those with specificity for the tyrosinase, resulting in the increased tumor volume." (PMID 34375446, 2021). "TYR levels positively correlated with tumor size, with patients affected by a small tumor showing undetectable levels of TYR transcript for the entire period of follow-up (17–32 months)." (PMID 34885029, 2021). "Sufficient l-tyrosine is seemingly present in the tumor microenvironment for the secreted tyrosinase to produce melanin, and accumulation of E-Tyr was already detectable by 10 h after systemic injection in our tumor-bearing mice." (PMID 34952915, 2021). "The topical application of fermentation extracts or fatty acids has been shown to decrease UV-induced skin hyperpigmentation by regulating tyrosinase degradation." (PMID 34099789, 2021). "This demonstrates that MSOT can routinely detect melanin produced by tyrosinase-expressing bacteria deep in the tumor." (PMID 34952915, 2021). "In the formation of skin hyperpigmentation, tyrosinase is a key regulatory enzyme in the proliferation of browning pigments." (PMID 34885832, 2021). "Tyrosinase inhibitors have attracted considerable attention in improving tumor immunity, such as imatinib, an antitumor drug against chronic myelogenous leukemia." (PMID 31897975, 2020). "As a novel small molecule tyrosinase inhibitor, anlotinib can effectively inhibit angiogenesis and improve the perfusion of tumor tissues." (PMID 32366856, 2020). "Similar findings were observed for affinity‐maturation selections against other protein targets, including the tumor‐associated antigens CAIX and tyrosinase." (PMID 33240760, 2020).
tumor (continued). "To ensure that the tumors were the result of outgrowth of 4C-HA-MITF transformed cells, we investigated and confirmed the levels of HA-MITF and SOX10 in the tumor xenografts by Western blotting and RT-PCR, and TYR by RT-PCR." (PMID 32605315, 2020). "The seed is commonly used in well-known traditional Chinese medicine, and it has anti-tumor, p-glycoprotein and tyrosinase inhibitory activities." (PMID 33366944, 2020). "The use of tyrosinase inhibitors is one way to achieve skin hypopigmentation as tyrosinase is a key enzyme for the synthesis of melanin, which determines the skin and hair color." (PMID 32575468, 2020). "The results revealed that inhalation of eCPMV significantly reduced the tumor burden which was confirmed by assessing tyrosinase expression and metastatic‐like tumor foci in the lungs of B16F10 tumor bearing mice." (PMID 31456339, 2020). "In considering only the TYR point mutation/deletion, this represents 28.6% of the AHM compared with 3.0% of PM and 3.7% of other tumor samples (P = 0.021 and 0.026 respectively)." (PMID 32966289, 2020). "In tumor cells, tyrosinase expression level is significantly up-regulated than in normal cells along with increase of tyrosinase activity." (PMID 31897975, 2020). "Regarding the tyrosinase inhibitory activity, walnut septum extract showed very good results, therefore, this by-product can be further used in cosmetic products to treat skin hyperpigmentation as well as to inhibit wrinkle formation." (PMID 30380713, 2018). "On the contrary EP and MNI being in a pre-EMT phase, showed a higher expression of AP2α and Tyrosinase, thus indicating an earlier stage in tumor progression." (PMID 30290833, 2018). "Results indicated the occurrence of EMT together with low expressions of AP2α and Tyrosinase in PI and MI cells, in line with an advanced tumor stage." (PMID 30290833, 2018). "Accordingly, tyrosinase inhibitors are mainly used as chemical agents to reduce food browning and human skin hyperpigmentation." (PMID 30050651, 2018). "In spite of their common origin from the neural crests and the shared expression of differentiation antigens (e.g., MART-1, gp100, and tyrosinase), cutaneous melanoma is highly immunogenic, whereas UM is considered as a poorly immunogenic tumor." (PMID 28229253, 2017). "At week 4 post-implantation, around 50% of analyzed LNs were colonized by tumor cells, showing positivity for tyrosinase, and they were classified as metastatic sentinel LNs." (PMID 28128294, 2017). "Different technical approaches have been used to detect or isolate UM CTCs, including immunomagnetic sorting, enrichment by size of tumor cells, or RT-PCR detection of tyrosinase and MelanA/MART1 mRNA." (PMID 28229253, 2017). "Immunohistochemical analyses were performed on the ear sponge sections to investigate the distribution of lymphatic vessels (LYVE-1+, blue staining) and tumor cells (tyrosinase+, pink staining) at 2 and 4 weeks after sponge implantation." (PMID 28128294, 2017). "We also generated a murine form of these tyrosinase-specific Tregs, and when transferred in vivo, the cells were capable of suppressing anti-tumor immunity in murine tumor models." (PMID 29123516, 2017). "The presence of tyrosinase positive tumor cells was seen in 100% of sponges soaked with tumor cells." (PMID 28128294, 2017). "The tumor cells were detected by immunostaining for tyrosinase + gp100 + Melan-A (together PanMel) or MCSP, and the T cells and cytolytic T cells by immunostaining for CD3 and CD8, respectively." (PMID 27484791, 2016). "Consistent with the melanotic phenotype of the tumor, elevated expression of tyrosinase was observed." (PMID 27519597, 2016). "IHC analysis revealed the expression of tyrosinase by malignant cells, thus confirming the melanocytic origin of tumours." (PMID 27166257, 2016).
tumor (continued). "In this study, we successfully demonstrated that a TYR gene for MR imaging combined with the tumor target of an hTERT promoter can be used to diagnose tumors in vitro and in vivo." (PMID 27283901, 2016). "PDK1 inhibition has been shown to have powerful and broad spectrum anti-tumor effects in vitro, and these effects are relatively unique compared to tyrosinase inhibitors." (PMID 26593251, 2016). "Fontana-Mason staining of 8 μm tumor sections confirmed melanin granules exclusively within cells of the +TYR tumors, suggesting that tyrosinase expression was capable of producing melanin in vivo with DOX induction." (PMID 24936769, 2014). "One week after tyrosinase induction with DOX, +TYR tumors were visually darker than -TYR tumors as determined by eye and half mm tumor sections, suggesting that melanin was produced in +TYR tumors." (PMID 24936769, 2014). "Initial evaluations revealed that tyrosinase is an independent prognostic marker for tumor progression." (PMID 25667918, 2014). "The flavenoid broussochalcone A is the principal inhibitor of cholinesterase, tyrosinase and xanthine oxidase and also exhibits potent anti-tumor activity." (PMID 24848504, 2014). "Six mice were analyzed which had both a +TYR and –TYR tumor, and each subject was imaged before and after DOX treatment." (PMID 24936769, 2014). "Two approaches were taken to transfect tumor cell lines to incorporate an inducible tyrosinase reporter system." (PMID 24936769, 2014). "This xenogenic vaccine utilises the 92% homology of human and canine tyrosinase to produce a tyrosinase-specific anti-tumour response." (PMID 24196087, 2013). "In our work, we successfully demonstrated that TYR can be used as a MRI reporter both in vitro and in vivo while achieving excellent tumor contrast." (PMID 23508226, 2013). "Collectively, these results suggested that the PLA nanocapsule containing polyHb-Tyr had the ability to inhibit the tumor cells proliferation and the tyrosinase contributed to the major effect." (PMID 23209910, 2012). "With regard to tumor Ag vaccines, in a trial with MART-1, gp100 and tyrosinase peptides in metastatic CM patients, one of the patients who experienced a dramatic tumor regression had preexisting immunity to TRP2 and NY-ESO-1 Ag." (PMID 22924051, 2012). "At 48 hours, the tumour cells growth was most effectively inhibited in the groups of 40 units and 200 units of tyrosinase activity." (PMID 23209910, 2012). "The result showed that PLA nanocapsule [polyHb-Tyr] inhibited tumor proliferation, and the effect was tyrosinase dose dependence." (PMID 23209910, 2012). "Compared with the control group, the higher the tyrosinase activity the greater was the inhibition of tumour proliferation as shown by the decrease in cell viability at 24 hours and 48 hours." (PMID 23209910, 2012). "Among CM Ag outstands melanocyte differentiation Ag (MD-Ag) such as MART-1, gp100, tyrosinase, tyrosinase-related protein-1 (TRP1), TRP2, and MELOE-1; cancer-testis Ag from the MAGE super-family and NY-ESO-1; and tumor-mutated Ag such as BRAF." (PMID 22924051, 2012). "Using this methodology in a model tumor system, murine Tregs designed to express the tyrosinase TCR effectively blocked antigen-specific effector T cell (Teff) activity as determined by tumor cell growth and luciferase reporter-based imaging." (PMID 20668510, 2010). "SEREX has been applied to a wide range of tumour types, “novel” as well as previously defined tumour antigens have been identified using SEREX, including MAGE-1 and tyrosinase, originally identified as tumour antigens recognised by CTLs." (PMID 18949081, 2008). "Logistic regression multivariante analysis indicated that each single marker (except tyrosinase) and more especially, the presence of PCR-positive markers remained a statistically independent prognostic factor for tumour progression." (PMID 12107840, 2002).